EEF2K (eukaryotic elongation factor 2 kinase)
Description:
Threonine kinase that regulates protein synthesis by controlling the rate of peptide chain elongation. Upon activation by a variety of upstream kinases including AMPK or TRPM7, phosphorylates the elongation factor EEF2 at a single site, renders it unable to bind ribosomes and thus inactive. In turn, the rate of protein synthesis is reduced.
Synonyms: eEF-2K; CaMKIII; HSU93850
Tractability: Small molecule: a structure with a bound ligand is known; a high-quality ligand is known; it belongs to a druggable protein family. PROTAC: it is named in the literature on targeted protein degradation; ubiquitination databases record sites on it; its protein half-life has been measured; a small molecule that binds it is known.
Target class: Atypical protein kinase group; Protein Kinase; Kinase; Enzyme; Atypical protein kinase alpha family
Gene: Protein-coding gene on chromosome 16 (22,206,272 to 22,288,738, forward strand). Ensembl gene ENSG00000103319.
Subcellular location (Human Protein Atlas): Nucleoplasm
Pathways (Reactome):
Signal Transduction: mTORC1-mediated signalling
Gene Ontology:
Molecular function: calmodulin binding; elongation factor-2 kinase activity; protein kinase activity; translation factor activity, RNA binding; ATP binding; calcium ion binding; protein serine/threonine kinase activity
Biological process: protein autophosphorylation; regulation of translation at postsynapse; translational elongation; cellular response to anoxia; cellular response to brain-derived neurotrophic factor stimulus; cellular response to calcium ion; cellular response to cAMP; cellular response to insulin stimulus; negative regulation of apoptotic process; positive regulation of dendritic spine morphogenesis; positive regulation of endocytosis; positive regulation of synapse assembly; response to ischemia; response to prolactin
Cellular component: cytoplasm; cytosol; postsynaptic density; dendritic spine; glutamatergic synapse
Genetic constraint (gnomAD): Loss-of-function variants: 68 observed, 92.9 expected, observed/expected ratio (o/e) 0.73, 90% interval 0.6 to 0.9. The upper end of that interval is the gene's LOEUF score, 0.9, which puts it in group 3 of 6, group 1 being the genes least tolerant of losing a copy. Missense variants: 919 observed, 985.6 expected, observed/expected ratio (o/e) 0.93, 90% interval 0.88 to 0.99. Synonymous variants: 370 observed, 384.56 expected, observed/expected ratio (o/e) 0.96, 90% interval 0.88 to 1.05.
Homologues: Orthologues: chimpanzee EEF2K (99% identical), macaque EEF2K (97% identical), rabbit EEF2K (92% identical), pig EEF2K (90% identical), rat Eef2k (90% identical), mouse Eef2k (89% identical), guinea pig EEF2K (88% identical), dog EEF2K (86% identical), tropical clawed frog eef2k (72% identical), zebrafish eef2k (62% identical), Caenorhabditis elegans efk-1 (40% identical). Paralogues in human: HSPA12B (15% identical), HSPA12A (13% identical), ALPK2 (12% identical), ALPK1 (11% identical).
Diseases named in the same sentence as EEF2K in open-access papers:
EEF2K is named in the same sentence as 86 diseases in open-access papers, as found by Europe PMC text mining. Sharing a sentence is not in itself a finding about the gene and the disease. The quoted sentences say what the papers report.
breast carcinoma (29 papers, 1999 to 2026). "The figure demonstrates that high eEF2 K expression is associated with poor patient survival in several subtypes of breast cancer." (PMID 40266550, 2026). "Due to its effect, eEF2 K is overexpressed in many tumor types, including breast cancer, and this overexpression is associated with poor prognosis and resistance to treatment." (PMID 40266550, 2026). "In breast cancer cells in vitro, depletion of eEF2K by RNA-mediated interference was associated with decreased levels of the ‘pro-oncogenic’ proteins c-Myc and cyclin D1, and higher levels of the cell cycle inhibitory protein p27Kip1." (PMID 29186827, 2017). "In agreement with Edu results, silencing eEF-2K caused an accumulation of cells in the G0/G1 population and a reduction in S and G2/M population in everolimus-treated breast cancer cells, indicating that suppression of eEF-2K further caused G0/G1 cell cycle arrest induced by mTOR inhibitor." (PMID 33144562, 2020). "While it still remains unclear precisely how the down-regulation of eEF-2K affects these changes, our data suggest that eEF-2K may promote the expression of certain proteins associated with tumorigenesis in breast cancer cells." (PMID 22911754, 2012). "Recently, eEF2 K has been actively investigated as a therapeutic target for breast cancer, and many eEF2 K inhibitors, such as NH125, TX- 1918, A- 484954, and fluoxetine, etc., have been developed." (PMID 40266550, 2026). "Recent studies have also shown that eEF2 K is overexpressed in various other solid tumors, including pancreatic cancer, colon cancer, glioblastoma, and breast cancer, making it a potential therapeutic target in cancer treatment." (PMID 40266550, 2026). "Among these designed molecules, compound 11 l effectively degraded eEF2K and induced apoptosis in breast cancer cell lines, though its specificity and mechanism require further investigation." (PMID 40624025, 2025). "Our current study provides the first evidence that Rabeprazole and Pantoprazole can bind to FOXM1 and inhibit its activity and downstream signaling, including eEF2K and pEF2, in breast cancer cells." (PMID 38918225, 2024). "EEF2K has been reported to reduce the expression of PKM2 in breast cancer, and interact with PKM2 to regulate the phosphorylation of STAT3 in lung cancer." (PMID 35184394, 2022). "EEF2K can positively help to improve breast cancer cells' survival ability under nutrient deprivation or insufficient growth factor." (PMID 36601599, 2022). "It has been shown that eEF2K is overexpressed and regulates tumor progression in several types of malignancies, including breast cancer, glioma cancer, pancreatic cancer, lung cancer, neuroblastoma, and colorectal cancer." (PMID 33673713, 2021). "In triple-negative breast cancer (TNBC) cells, the proto-oncogene transcription factor forkhead box M1 (FOXM1) can regulate eEF2K and affect breast cancer cell migration and invasion, progression, and tumorigenesis." (PMID 33673713, 2021). "Silencing eEF2K suppresses the growth and induces apoptosis of breast cancer cells to a drug, doxorubicin." (PMID 34532346, 2021). "An anticancer drug, mitoxantrone, a potential inhibitor for eEF2K, can disrupt mTOR inhibitors to enhance the efficacy of anticancer effects in breast cancer cells." (PMID 34532346, 2021). "It was additionally shown that silencing eEF2K induces caspase-9 cleavage and Bcl-2 downregulation in breast cancer cells." (PMID 33673713, 2021). "Meanwhile, inhibiting eEF2K enhances the effect of doxorubicin in an orthotopic model of breast cancer." (PMID 33673713, 2021). "eEF2K and 4EBP1 were then transiently knocked-down in the different breast cancer cell lines and impact on growth was determined by MTT assay, which measures redox potential of viable mammalian cells." (PMID 33911160, 2021). "The upregulation of eEF2K accelerates glycolysis to promote human breast cancer cells in development and progression." (PMID 33673713, 2021).
breast carcinoma (continued). "We further demonstrated that mitoxantrone binds to eEF-2K and inhibits its activity, and the combination treatment of mitoxantrone and mTOR inhibitor resulted in significant synergistic cytotoxicity in breast cancer." (PMID 33144562, 2020). "The Ca2+/CaM-dependent kinase eEF2K/CaMK-III is overexpressed in triple-negative human breast carcinomas." (PMID 31991573, 2020). "To further demonstrate the effect of eEF-2K suppression on the sensitivity of mTOR inhibitor against breast cancer cell, we compared the cell viability in response to combined treatment of mTOR inhibitor with eEF-2K siRNA or Beclin 1 siRNA." (PMID 33144562, 2020). "Meric-Bernstam and colleagues found that EEF2K was overexpressed in breast cancer and, importantly, the expression of EEF2K was positively correlated with poor prognosis in breast cancer patients." (PMID 31266475, 2019). "Previous studies have reported increased expression of EEF2K in breast cancer and glioma, where it plays a critical role in cell cycle, autophagy and apoptosis making it a potential target for cancer therapy." (PMID 30008265, 2018). "In an orthotopic mouse model of breast cancer, siRNA-mediated silencing of eEF2K sensitised cells to the pro-apoptotic effect of doxorubicin." (PMID 29186827, 2017). "Recently, emerging evidence has revealed that eukaryotic elongation factor 2 kinase (eEF2K) is a potential molecular driver in several cancers, including pancreatic, brain and breast cancer." (PMID 28036267, 2017). "To elucidate the clinical significance of eEF2K protein expression, we first analyzed TCGA database and determined the prognostic value of eEF2K in 58 breast cancer patients with basal subtype." (PMID 28036267, 2017). "eEF2K plays a role in protecting breast cancer cells against endoplasmic reticulum (ER) stress, apparently by activating autophagy." (PMID 29186827, 2017). "A number of studies have reported a role for eEF2K in activating autophagy, largely using glioma cells, and also in breast cancer cell lines treated to induce endoplasmic reticulum stress." (PMID 29186827, 2017). "We recently demonstrated that eEF2K promotes breast cancer cell proliferation, clonogenicity, invasion, tumorigenesis, and resistance to chemotherapeutics by inducing clinically significant signaling pathways." (PMID 26918606, 2016). "In the present study, knockdown of FOXM1 led to a marked reduction in cyclin D1 expression, which was recently shown to be regulated by eEF2K in breast cancer cells." (PMID 26918606, 2016). "Yang and colleagues have demonstrated a cytoprotective role for eEF-2K in glioma and breast cancer cells." (PMID 22911754, 2012). "Further study is needed to determine the effect of clinically relevant doses of PI3K/mTOR pathway inhibitors in vivo, and their effect on eEF2K low- and high-expressing hormone receptor-positive breast cancers." (PMID 23102376, 2012). "We have shown for the first time that the targeting of eEF-2K in an in vivo orthotopic model inhibits growth of established breast cancer tumors and sensitizes the tumors to doxorubicin, an important agent in a number of chemotherapy regimens." (PMID 22911754, 2012). "We investigated the therapeutic potential of targeting eEF-2K systemically in an orthotopic model of breast cancer (MDA-MB-231) in nude mice." (PMID 22911754, 2012). "In addition to its involvement in cell migration, invasion, and tumor growth, we have previously demonstrated that eEF2K induces chemoresistance in breast cancer cells and confers resistance to cellular stress." (PMID 40624025, 2025). "The inhibition of eEF2K has been shown to arrest breast cancer cells at the G0/G1-S phase." (PMID 33673713, 2021). "Among a series of synthesized analogues with linkers of various chain length and constitution, compound 11 (“11l”) had the maximum eEF2K degradation rate (Dr) value of 56.7% and could induce apoptosis in human breast carcinoma MDA-MB-231 cells in vitro." (PMID 33673713, 2021).
breast carcinoma (continued). "Increasing evidence shows that eEF2K is highly expressed in a variety of tumor tissues and that it is related to the development and prognosis of several kinds of malignancies such as breast cancer, ovarian cancer, colon cancer, glioma, medulloblastoma, hepatocellular carcinoma, and prostate cancer." (PMID 33673713, 2021). "Therefore, disruption of eEF-2K simultaneously abrogates the two critical resistance signaling pathways, sensitizing breast cancer cells to rapalogs." (PMID 33144562, 2020). "In addition, NH125, a commercial eEF-2K inhibitor, also suppressed the activation of Akt in everolimus-treated breast cancer cells." (PMID 33144562, 2020). "In addition, we found that NH125, a well-known eEF-2K inhibitor, also further augmented mTOR inhibitor-induced cytotoxicity in breast cancer cells." (PMID 33144562, 2020). "Moreover, similar data were obtained in an orthotopic model of breast cancer using RNA interference (RNAi) suppression of eEF2K, and by pharmacological inhibition of eEF2K in triple-negative murine breast cancer cells." (PMID 32298235, 2020). "We next wanted to know whether mitoxantrone can augment mTOR inhibitor-induced cytotoxicity in breast cancer cells by inhibiting eEF-2K." (PMID 33144562, 2020). "Furthermore, breast cancer cells with eEF-2K knockdown and rapamycin formed fewer colonies, as compared with cells treated with everolimus alone." (PMID 33144562, 2020). "In this study, we demonstrated that eEF-2K is an important mediator in the activation of Akt and autophagy induced by rapalogs, and inhibition of eEF-2K can turn off both cytoprotective pathways and significantly enhanced the anti-proliferation effect of rapalogs in breast cancer cells." (PMID 33144562, 2020). "In an orthotopic model of breast cancer, siRNA-mediated knockdown of eEF2K slowed tumour growth." (PMID 29186827, 2017). "Overall, these results suggest that FOXM1 is involved in eEF2K expression in breast cancer cells." (PMID 26918606, 2016). "We first examined previously reported indirect downstream targets of eEF2K in breast cancer cells." (PMID 26918606, 2016). "To further evaluate the ability of eEF-2K knockdown to sensitize breast cancer cells to doxorubicin, we decided to assess whether eEF-2K knockdown sensitized MCF-7 cells that are resistant to doxorubicin (MCF-7/DoxR cells)." (PMID 22911754, 2012). "We also provide the first in vivo data using an orthotopic model to support the notion that targeting eEF-2K may be a useful strategy as a co-therapy for breast cancer to enhance efficacy of commonly used chemotherapeutic agents, such as doxorubicin." (PMID 22911754, 2012). "Taken together, our data indicate that targeting eEF-2K in combination with chemotherapy may be a therapeutic strategy for the treatment of breast cancer." (PMID 22911754, 2012). "Mechanisms regulating the activity of eEF-2K in breast cancer cells are not well understood." (PMID 22911754, 2012). "In the basal-like, lymph-node positive group (PAM50), high eEF2 K expression was significantly associated with reduced RFS (HR = 1.85, log-rank p = 0.015), suggesting that eEF2 K may play a role in promoting tumor recurrence in more aggressive forms of breast cancer." (PMID 40266550, 2026). "Elongation factor 2 kinase (eEF‐2K) belongs to the atypical group of kinases and plays an important role in maintaining cellular homeostasis and tumor‐cell survival and proliferation, making eEF‐2K a potential target for cancer treatment, notably breast cancer." (PMID 39287197, 2025). "previously demonstrated that EEF2K could inhibit the expression of PKM2 in breast cancer." (PMID 35184394, 2022). "In this study, we found that eEF-2K, which is overexpressed in cancer cells and is required for survival of stressed cells, was involved in the negative-feedback activation of Akt and cytoprotective autophagy induction in breast cancer cells in response to mTOR inhibitors." (PMID 33144562, 2020).
breast carcinoma (continued). "Our data suggest that eEF-2K may enhance tumorigenesis through the up-regulation of pro-tumorigenic proteins and pathways including cyclin D1, c-Myc, c-Src/FAK and Akt whose dysregulation are associated with a poor prognosis in breast cancer." (PMID 22911754, 2012). "In this study we provide the first evidence that systemic in vivo targeting of eEF-2K expression by liposomal siRNA inhibits growth and induces apoptosis of established tumors in an orthotopic xenograft model of a highly aggressive and metastatic breast cancer." (PMID 22911754, 2012). "Overall, these findings highlight eEF2 K as a potential biomarker for poor prognosis in TNBC and basal-like breast cancer, particularly in terms of OS and RFS." (PMID 40266550, 2026). "Additionally, eEF2K expression has been linked to the induction of epithelial-mesenchymal transition (EMT), migration, invasion, and chemoresistance in various cancers, including pancreatic, lung, breast cancer, and glioma, further supporting its oncogenic role in solid tumors." (PMID 40624025, 2025). "Additive effects were seen between eEF2K and glutamine-starvation in 4 of 5 different TNBC cells, as well as in luminal MCF7 breast cancer cells." (PMID 33911160, 2021). "It has been found that hypoxia inhibits protein synthesis in breast cancer cells in part through 4E-BP1 and the eEF2K pathway, controlled by mTOR." (PMID 33673713, 2021). "In breast cancer cells (MCF-7 and MDA-MB-468), during nutrient deprivation or treatment with inhibitors of growth factor receptors, eEF2K is activated due to inhibition of the mTORC1/S6 kinase pathway." (PMID 29186827, 2017). "In breast cancer cells, nutrient and growth factor withdrawal decreases ATP and activates Ca2+/calmodulin-dependent protein kinase III, the eukaryotic elongation factor-2 kinase (eEF-2 kinase)." (PMID 23847620, 2013). "Previous studies have reported that eEF-2K knockdown sensitizes glioma cells to TRAIL, 2-deoxy-D-glucose and the Akt inhibitor MK-2206, as well as breast cancer cells to the inhibition of growth factor receptor signaling." (PMID 22911754, 2012). "In this study, we sought the effect of eEF2 K-siRNA by supporting quercetin (QU) molecules, known as a chemotherapeutic agent in a novel hybrid nanoparticle (HNP) developed as applying LbL method, on TNBC-type breast cancer." (PMID 40266550, 2026). "Because FOXM1 is also involved in these functions in breast cancer cells, we hypothesized that FOXM1 may transcriptionally regulate eEF2K expression." (PMID 26918606, 2016). "Increased eEF-2K activity has been reported in breast cancer specimens, but is absent in normal adjacent tissue." (PMID 22911754, 2012). "As eEF-2K is reported to play a role in the invasiveness of human glioma cells, we wondered whether it might also regulate the invasiveness of MDA-MB-231 breast cancer cells, which have a highly invasive phenotype." (PMID 22911754, 2012). "Early studies using the non-specific compound rottlerin suggested that eEF-2K is important for the proliferation of breast cancer cells." (PMID 22911754, 2012). "Importantly, these studies are supported by clinical data showing a negative correlation between eEF2K expression and patient prognosis in medulloblastoma, glioblastoma multiforme and breast cancer." (PMID 32298235, 2020). "For example, in breast cancer (BRCA), especially triple‐negative breast cancer (TNBC), eEF2K is often overexpressed, contributing to poor patient prognosis by promoting cancer cell survival under conditions of metabolic stress." (PMID 39592671, 2024).